APOE (apolipoprotein E)
Diseases named in the same sentence as APOE in open-access papers (continued):
Sharing a sentence is not in itself a finding about the gene and the disease.
cognitive decline (continued). "Additionally, examining the differential impact of carrying one versus two copies of the APOE ε4 allele could provide insights into cognitive decline risk, though our study lacked the power to explore this due to the limited number of ε4/ε4 carriers (n = 2)." (PMID 39392181, 2024). "While a number of prior studies have reported greater rates of cognitive decline among cognitively normal APOE-ε4 carriers, studies examining the relationship of AD-PRS with cognitive decline have been more limited." (PMID 36978190, 2023). "APOE-ε4 and DSST were significant predictors of cognitive decline and dual decline, and 400 m walk was significant across all three groups." (PMID 36891556, 2023). "The apolipoprotein E (APOE) ε4 allele has been associated with cognitive decline in Parkinson's disease (PD), but little is known about its relationship with motor and other nonmotor symptoms and whether APOE ε4 retains an influence on cognition when other factors are considered." (PMID 38026513, 2023). "We have recently shown that both APOE ε4 and PRS for AD predicted aging-related cognitive decline across 25 years in individuals that remained healthy at follow-up, where the effect of PRS was seen already six years prior to diagnostic follow-up8." (PMID 37225733, 2023). "Thus, our findings suggested that APOE ε4 might boost the Aβ plaque deposition and tau accumulation especially in hippocampus during the full trajectory of AD progression, which further promote hippocampal atrophy and cognitive decline." (PMID 37323144, 2023). "Subgroup analyses were conducted to further investigate the longitudinal relationship between GFAP and cognitive decline using GLMM adjusted for age, sex, education, APOE ε4 carrier status, and disease duration." (PMID 37475029, 2023). "Statistically, this would be represented by a statistical interaction between APOE-ε4 and OCRS regarding cognitive decline." (PMID 36571008, 2022). "In patients with MCI, donepezil accelerates cognitive decline in homozygous BCHE-K and APOE-4 carriers." (PMID 35330211, 2022). "Further evidence is therefore required to determine how APOE-ε4 contributes to decreases in FFM and/or FM at each stage of cognitive decline." (PMID 35276898, 2022). "Patients harboring the APOE-ɛ4/BCHE-K* genotype show an earlier age of onset, an accelerated cognitive decline, and an irregular response to donepezil." (PMID 35330211, 2022). "It has been suggested that this haplotype (APOE-4/4-TOMM40-L/L) is responsible for premature neuronal death, early onset of the disease, accelerated cognitive decline, and a poor response to conventional treatments." (PMID 35330211, 2022). "Future longitudinal studies are necessary to determine if APOE genotype and AD biomarkers influence the trajectories of PWV and its relationship to cognitive decline as well as to explore some of the potential mechanisms underlying these relationships." (PMID 34210365, 2021). "Notably, in our exploratory analysis of individual genetic variants and rate of cognitive decline adjusting with and without APOE ε4 burdens resulted in the same variant rs10492328 as a top hit with similar p-value threshold (p = 4.4e−07) (supplementary results)." (PMID 34615922, 2021). "Thus, the hypothesis that PA might modify the association between APOE and cognitive decline was not supported by our results." (PMID 32110803, 2020). "A study in a smaller subjective cognitive decline (SCD) population employing the 3-Plex kit reported a higher age- and APOE-ε4 genotype-adjusted AUC (0.79) than in the first study, which employed the singleplex assays." (PMID 33278904, 2020). "APOE-ε4/BCHE-K* carriers show an earlier age of onset, an accelerated cognitive decline, and a differential response to donepezil therapy." (PMID 32357528, 2020).
cognitive decline (continued). "As assays to selectively measure the proportion of HDL particles containing apoE become more readily available, it will be important to determine whether the levels of circulating apoE-containing HDL help to predict the risk of CAA, total brain Aβ accumulation, and cognitive decline in AD patients." (PMID 32213187, 2020). "The risk for cognitive decline may also be highest in individuals who not only demonstrate elevated amyloid, but who are also carriers for the ε4 allele of the APOE gene, and we lacked sufficient sample size to permit such further stratification in our analyses." (PMID 31627738, 2019). "ANCOVA analysis of variance corrected, APOE apolipoprotein E, HC healthy control, SCD subjective cognitive decline, SUVr standardized uptake value ratio." (PMID 31286994, 2019). "The main factors that cause cognitive decline in APOE ε4 carriers may not relate to BG." (PMID 30984391, 2019). "A subsequent replication study also indicated that the rs4844609 SNP in the CR1 gene modulates episodic memory decline and an interaction between APOE and CR1 influences cognitive decline for normal aging and for pathological aging." (PMID 29209239, 2017). "Hence, the disparity between studies may reflect the fact that these genetic variants have time-dependent effects on cognition which vary with disease stage: MAPT seems to have its greatest impact on cognitive decline in early PD, whereas APOE may have a more pronounced effect in later disease." (PMID 27242557, 2016). "Yet not all individuals with an APOE-ε4 allele will develop AD, suggesting that other genetic, and possibly lifestyle, factors may offer protection from neurodegeneration that ultimately leads to cognitive decline and a diagnosis of clinical AD." (PMID 24795624, 2014). "A second caveat is that we only investigated indirect interactions between APOE, BDNF Val66Met, Aβ and cognitive decline in adults with aMCI." (PMID 24475133, 2014). "Finally, we wished to examine the effect of APOE ε4 allele on plasma ApoE levels, correlations of apolipoproteins with age and with lipid profiles, including total cholesterol, HDL-cholesterol, LDL-cholesterol and triglycerides, and the association of lipid profile with cognitive decline." (PMID 22701550, 2012). "We observed a significant gene-pathology interaction: APOE ε4 carriers demonstrated a steeper trajectory of cognitive decline for a given severity of CAA compared to non-carriers." (PMID 41996885, 2026). "To better understand the genetic architecture of cognitive decline, we conducted genome-wide meta-analyses on older adults in three APOE genotype groups: APOE2 carriers (APOE 2/2, 2/3), APOE3 homozygotes (APOE 3/3), and APOE4 carriers (APOE 3/4, 4/4)." (PMID 40725187, 2025). "An example of a non-pharmacological lifestyle intervention trial including APOE-ɛ4 carriers is the PENSA study which aims to prevent cognitive decline in older adults with subjective cognitive decline." (PMID 40000321, 2025). "If studies confirm a synergistic effect between ELA and genetic factors like APOE ɛ4 or FKBP5 on inflammation and cognitive decline, it could lead to targeted screening programs for individuals with both ELA history and genetic risk factors." (PMID 40001464, 2025). "Further studies with larger samples should explore whether APOE ε4 status moderates the relationship between DTI metrics and cognitive decline." (PMID 40763286, 2025). "Incorporating these biomarkers in future investigations would provide valuable insights into how serum Se levels relate to AD pathophysiology and cognitive decline, especially in APOE-negative older adults." (PMID 39940451, 2025). "Second, the parameters that have the most important impact on cognitive decline are not completely the same depending on sex and APOE status." (PMID 40771353, 2025).
cognitive decline (continued). "Studies such as have associated APOE ε4+ phenotype with MCI/AD and its pathology, as well as accelerated cognitive decline in APOE4 carriers compared to non-carriers." (PMID 41583006, 2025). "We observed a significant APOE-ε4 x sex x FTX interaction on longitudinal cognition (p = 0.03), whereby the male-specific protective effect of FTX expression on cognitive decline was driven by APOE-ε4 carriers (β = 0.05, p = 0.01)." (PMID 40166028, 2025). "These values suggest that while APOE ε4 positivity raises the likelihood of cognitive decline, a large proportion of affected patients will not be captured by genetic screening alone." (PMID 41153256, 2025). "Several studies have found that veterans carrying APOE ε4 in conjunction with a probable history of TBI and/or PTSD have more severe symptoms, worse long-term neuropsychiatric outcomes, and higher rates of cognitive decline than their non-ε4 counterparts." (PMID 39931547, 2025). "However, the precise mechanisms by which ApoE ε4 influences GSK‐3β activity and exacerbates brain pathology and cognitive decline in T2DM patients remain poorly understood." (PMID 40905109, 2025). "Studies suggest that interactions between APOE ε4 and other genes, such as ABCA7, may accelerate cognitive decline and neurodegeneration." (PMID 40565005, 2025). "In contrast to our analysis, the research did not model the interaction of cognitive decline and APOE and only included Aβ abnormality." (PMID 40167963, 2025). "Post hoc interaction analyses revealed significant synergistic associations between white matter abnormalities and key AD endophenotypes, including hippocampal volume, SPARE-AD index, APOE ε4 positivity, and amyloid PET positivity, in predicting poorer memory and accelerated cognitive decline." (PMID 40513084, 2025). "In contrast, a large study with rosiglitazone at 3 different doses over 24 weeks revealed significant cognitive improvement at the highest dose (8 mg) in APOE ε4 non-carriers, whereas APOE ε4 carriers experienced some cognitive decline." (PMID 41146261, 2025). "Analyses will be stratified by APOE genotype (ε4 carriers vs. non-carriers) and pre-stroke cognitive decline (IQCODE > 3.48 vs. IQCODE ≤ 3.48) to assess for effect modification by these factors." (PMID 38570800, 2024). "However, evidence on the longitudinal association between HZ and cognitive decline is conflicting and whether the risk differs by APOE ε4-carrier status has not been studied; prospective cohort studies on the association between HZ vaccination and cognitive decline are also lacking." (PMID 39138535, 2024). "Among the rest of the gene variants studied, neither the APOE ε7 allele nor the PSEN-1 Glu318Gly mutation were directly associated with SCD and longitudinal cognitive decline, even though these were found only in the SMC groups." (PMID 38534745, 2024). "Independent of genotype, low abundance of apolipoprotein E (apoE), is characteristic of AD CSF, and predicts cognitive decline." (PMID 35484240, 2024). "Subgroup analyses revealed that lecanemab had a more pronounced effect in slowing cognitive decline in individuals who are ApoE ε4 noncarriers compared to carriers and had the least impact on participants who were ApoE ε4 homozygotes." (PMID 38565747, 2024). "Higher than normal adropin levels thus still correlate with protection from cognitive decline irrespective of APOE genotype." (PMID 37233882, 2024). "Further, PRS predicts longitudinal cognitive decline in cognitively normal individuals with and without high tau and Aβ burden at autopsy, and among APOE ε4 non-carriers." (PMID 38230720, 2024). "Elevated sPDGFRβ in CSF was shown to indicate pericyte injury and BBB breakdown and predict future cognitive decline in APOE ε4 carriers but not in non-carriers independent of AD pathology." (PMID 37213537, 2023).
cognitive decline (continued). "Our results show that APOE-ε4 carriers with Aβ VR+ in late amyloid accumulation regions exhibited a significantly steeper cognitive decline compared with non-carriers." (PMID 36856866, 2023). "Hereby, we chose to adjust for age, gender, baseline cognitive level, APOE ε4 carrying status and Aβ status for further investigation, and eventually found that there was still a predominant relationship between CSF GFAP and cognitive decline." (PMID 37475029, 2023). "For instance, FTD patients carrying the APOE4 genotype display earlier onset tau pathology, more severe neurodegeneration, and greater cognitive decline than non-APOE4 carriers, suggesting APOE may influence tau pathology independently of Aβ pathology." (PMID 37445986, 2023). "Our results suggest that higher levels of CR differentially mitigate APOE-ε4-related vs. AD-PRS-related cognitive decline, with the protective effect of CR being specific to APOE-ε4-related declines in episodic memory (but not executive function)." (PMID 36978190, 2023). "Third, we show that the relationship between APOE e4 and long-term cognitive decline is largely independent of childhood cognitive ability, an important confound (but rarely available measure) in studies of cognitive ageing." (PMID 36481934, 2023). "Specifically, APOE-ε4 carriers who were VR+ in lateral temporal regions and in the striatum displayed a significantly steeper cognitive decline, as measured with the PACC, than non-carriers and VR- individuals." (PMID 36856866, 2023). "Higher Aβ PET also predicted faster hippocampal atrophy over time in APOE-ε4 carriers only, but was related to faster cognitive decline regardless of APOE-ε4 status." (PMID 35351867, 2022). "The presence of the APOE-ε4 allele was associated with lower fat mass, particularly in women with MCI, independent of cognitive decline." (PMID 35276898, 2022). "Here, we recognize the strongest known genetic risk factor for LOAD (APOEε4) and investigate its effect on mid‐age individuals who have no apparent symptoms of cognitive decline, comparing them to the more common APOE genotype (APOEε3)." (PMID 36408825, 2022). "Evidence has shown that participants with milder symptoms and without apolipoprotein E (APOE) ε4 allele are more likely to reverse to normal cognition, and healthy lifestyles including exercise and diet can prevent or reverse cognitive decline." (PMID 36684932, 2022). "This would argue for an independent effect of pRBD and APOE ɛ4 status without a synergistic effect on cognitive decline in iPD." (PMID 36245388, 2022). "It is important to note that in our study we did not aim to test correlations between cognitive decline and the APOE genotype, as this is well known from the literature." (PMID 36292001, 2022). "A cohort study showed a significant interaction between a DM history and the APOE genotype, in which any DM history affected the cognitive decline in APOE4-negative older adults, but not in APOE4-positive older adults." (PMID 36466611, 2022). "In de novo PD patients aged >65, male, ill-educated (<13 years) and without carrying APOE ε4, we found the predictive effects of CSF NfL baseline concentration and longitudinal rate on cognitive decline appeared to be more remarkable and comprehensive." (PMID 36589544, 2022). "Baseline GBA status did not predict progression of any of the measures while APOE status predicted a more rapid cognitive decline (MOCA Coefficient −0.43, p<0.001)." (PMID 35577512, 2022). "Another key finding of this study was that age-related WMH increase predicted longitudinal hippocampal atrophy and cognitive decline in APOE-ε4 non-carriers." (PMID 35351867, 2022). "Higher Aβ PET also predicted faster rates of aHCV (p = 0.010) in APOE-ε4 carriers only, but was related to faster rates of cognitive decline (p < 0.022) regardless of APOE-ε4 status." (PMID 35351867, 2022).
cognitive decline (continued). "Fourth, we did not analyze the impact of the different biomarkers or APOE on progression or cognitive decline and we based all the diagnosis and progression on clinical criteria." (PMID 35930282, 2022). "In our study, APOE ε4 allele carrier status did not have a significant interaction with OAB AC use and a clinically significant cognitive decline." (PMID 36506252, 2022). "In summary, APOE and SORL1 might be the most important genetic factors related to cognitive decline in Han Chinese population." (PMID 34214049, 2021). "In our study, changes in cognitive decline with aging, female APOE ε4 carriers were found to be the most sensitive, in contrast with female APOE ε4 noncarriers, male APOE ε4 carriers, and male APOE ε4 noncarriers." (PMID 34616288, 2021). "In contrast, some studies reported the effect of cholesterol on cognitive function was independent of APOE, and the high-cholesterol subgroup had a higher cognitive decline rate than the normal-cholesterol subgroups with or without APOE ε4." (PMID 34483892, 2021). "Our finding that APOE ε4 aggravated cognitive decline across the entire AD spectrum regardless of sex is partially consistent with previous studies." (PMID 33603015, 2021). "The authors commented that some previous studies had shown accelerated cognitive decline in APOE-ε4 homozygotes but not heterozygotes." (PMID 34205498, 2021). "Compared to APOE ε4 noncarriers, APOE ε4 carriers had slower cognitive decline in general cognitive function (MMSE, and CDR-SB, P = .009 and 0.019), language (P = .017), memory (P = .011), and frontal-executive function (P = .001)." (PMID 34127075, 2021). "Contrary to analyses including the temporal meta‐ROI, CSF p‐tau217 was no longer independently associated with age and APOE ɛ4 carriership, and the stronger associations between tau PET and cognitive decline in the symptomatic stage were no longer found." (PMID 34254442, 2021). "The reason why EOAD showed more rapid cognitive decline in the absence of APOE ε4 needs further studies." (PMID 34127075, 2021). "After 11 years of follow-up, the 5 blood-based markers that correlated best with cognitive decline were APOE (present/absent), cystatin C, serum glucose, CRP, and IL-6." (PMID 33946285, 2021). "Our analyses also suggested APOE carrier status was independent of SMC severity ratings when predicting cognitive decline." (PMID 33692711, 2021). "In sensitivity analysis, the interaction effect between APOE/PRS for cognitive decline was not significant (p > 0.05)." (PMID 34041846, 2021). "The authors reported an association between moderate to high intake of n-3 PUFA and slower rates of cognitive decline among APOE ε4 carriers, but not among APOE ε4 non-carriers." (PMID 33573174, 2021). "Previous study showed that the associations of higher dietary n-3 fatty acids, EPA and DHA with slower cognitive decline are more pronounced among APOE ε4 carriers compared with ε4 non-carriers." (PMID 34355006, 2021). "APOE ε4 carriers showed slower cognitive decline in general cognitive function, language, and memory domains than APOE ε4 carriers in EOAD but not in LOAD." (PMID 34127075, 2021). "Third, other confounding factors, including apolipoprotein E genotype, frailty, and diet, are important factors for cognitive decline but were not assessed in this study because of limited funding." (PMID 34305783, 2021). "Of the individual AD features, subtle objective cognitive decline, APOE ε4 carriership, p-tau and tau but not CSF β-amyloid all accelerated functional decline." (PMID 34867762, 2021). "In conclusion, the claims of a gene–environment interaction between APOE ɛ 4 and PA in cognitive decline are not supported by our results." (PMID 32110803, 2020). "However, there was a subset of features that was retained as the 12 most important in both methods, namely, subjective cognitive decline (SCD), APOE, age, a diet rich in sweets, frequency of family relationships, and body mass index (BMI)." (PMID 33244011, 2020).